UBE2T (ubiquitin conjugating enzyme E2 T)
Diseases named in the same sentence as UBE2T in open-access papers (continued):
Sharing a sentence is not in itself a finding about the gene and the disease.
tumor (continued). "This variability, likely influenced by the complex tumor microenvironment, complicates the design of effective therapeutic strategies targeting UBE2T." (PMID 39791716, 2024). "First, functional analyses reveal that UBE2T acts as an oncogene that promotes tumorigenesis and progression, with its effects varying across different tumor types and cellular environments." (PMID 39791716, 2024). "In GBM, UBE2T enhances tumor progression and drug resistance by upregulating survivin and c-Myc via Wnt/β-catenin activation." (PMID 39791716, 2024). "In LUAD, UBE2T expression is upregulated, and this increased expression correlates with larger tumor size, lymph node metastasis, distant metastasis, and poor prognosis." (PMID 39791716, 2024). "By mediating the ubiquitination and degradation of the scaffolding protein RACK1, UBE2T hyperactivates the Wnt/β-catenin pathway, thereby promoting tumor growth." (PMID 39791716, 2024). "The dysregulation of UBE2T in lung cancer has been shown to initiate oncogenic signaling pathways, leading to tumor progression and metastasis." (PMID 39791716, 2024). "As a target for next-generation cancer diagnostics and therapeutics, UBE2T holds a promise for innovative strategies in tumor diagnosis and treatment." (PMID 39791716, 2024). "As a result, genes encoding ubiquitin conjugating enzymes or ligases, such as UBE2T, UBE2C, and CBLC, were up‐regulated in tumor tissues, while genes encoding deubiquitinating enzymes like OTUD1 and USP12 were down‐regulated." (PMID 37983609, 2024). "UBE2T confers chemotherapy resistance and promotes tumour growth by alleviating DNA replication stress." (PMID 39245797, 2024). "In summary, the current examination found that UBE2T expression was greater in tumor tissues from ES patients than in non-tumor tissues and that UBE2T had an important value as a biomarker for the diagnosis of ES." (PMID 36910645, 2023). "It was found that the expression level of KCTD12, SIAH1, TRIM58, UBE2S, and UBE2T were significantly decreased in tumor tissue compared with the normal tissue, but TRIM47 was upregulated." (PMID 36534449, 2022). "We investigated the clinical relevance of UBE2T in the different tumor types using Kaplan–Meier survival analysis regarding OS, DSS, DFI, and PFI." (PMID 36357897, 2022). "UBE2T not only involved in DNA repair but also regulated the protease in the glucose metabolism of tumor tissue, leading to its ubiquitination and degradation, ultimately promoting the tumor by glucose metabolism." (PMID 35444699, 2022). "TIMER and CIBERSORT were utilized in order to investigate the connection that exists between UBE2T expression and tumor-infiltrating immune cells." (PMID 36245987, 2022). "Cumulatively, our observations suggest that UBE2T leads to the activation of Wnt/β‐catenin pathway when conditions better mimic the 3D tumor microenvironment." (PMID 34614271, 2022). "In the analysis of another dataset (GSE25097), UBE2T was significantly upregulated in tumor specimens from normal to cirrhotic to tumor tissues in a stepwise manner, suggesting an oncogenic role for UBE2T in liver carcinogenesis." (PMID 33542213, 2021). "Elevated expression levels of UBE2T were observed in various malignant tumor tissues, which seem to relate to tumor size, the degree of malignancy, metastasis, and poor prognosis of tumor patients." (PMID 34257599, 2021).
tumor (continued). "Overall, these data indicated that the tumor-inhibitory effect of miR-543 was executed by downregulating UBE2T through the ERK/MAPK pathway." (PMID 34787051, 2021). "We confirmed the role of Mule as a tumor suppressor, as there was a reciprocal correlation between UBE2T and Mule expression in HCC cells upon overexpression and repression of UBE2T." (PMID 33542213, 2021). "Based on the gene expression data retrieved from the TCGA database, 4 of the 20 DEmRNAs (CAP2, CDKN3, MELK and UBE2T) were upregulated in tumor tissues, and the remaining DEmRNAs were upregulated in adjacent normal tissues." (PMID 33879119, 2021). "We found that mRNA and protein levels of UBE2T are obviously increased and UBE2T expression is positive correlated with tumor size, depth of invasion, lymph node metastasis, clinical stage, and poor prognosis." (PMID 33323973, 2021). "Accordingly, mechanisms underpinning the tumor-promoting roles of UBE2T have been intensively investigated." (PMID 34257599, 2021). "Different pathways, including PI3K/AKT, wnt/β-catenin, and GRP78, were involved in UBE2T-mediated tumor progression." (PMID 34703898, 2021). "Since polyubiquitin chains are known to play a key role in the regulation of tumor progression, UBE2T is regarded as a potential therapeutic target for tumors." (PMID 34703898, 2021). "When compared with control tumors, we found that UBE2T-repressed MHCC-97L cells exhibited a drastic reduction in tumor volume, as evidenced by an increase in liver weight." (PMID 33542213, 2021). "We obtained 7 pairs of HCC tissues and corresponding non-tumor tissues, and UBE2T was identified as one of the most upregulated genes." (PMID 33087136, 2020). "In this work, qPCR and western blot results revealed a significant increase in expression levels of TTLL12, MZT2B, CDC16 and UBE2T in GC tumor samples of diffuse and intestinal-type, when compared with normal gastric tissues." (PMID 33351778, 2020). "Considering the rapid tumor progression of ICC and the prominent role of UBE2T in tumor formation and development, in the present study, we performed corresponding research to investigate the effects of UBE2T on the diagnosis and prognosis of ICC." (PMID 32025379, 2020). "We found that UBE2T was significantly upregulated in HCC tissues compared to that in non-tumor tissues." (PMID 33087136, 2020). "Specifically, UBE2T plays an important role in the malignant transformation and tumor development of ICC." (PMID 32025379, 2020). "We further demonstrated that UBE2T functions as a tumour promoter in GBM by maintaining the protein level of GRP78." (PMID 32491994, 2020). "Results showed that of 133 HCC specimens, 79 (59.4%) showed high UBE2T expression, in comparison to only 10 (13.0%) out of 77 in the non-tumor tissue specimens." (PMID 33087136, 2020). "The results revealed significantly higher expression level of UBE2T in tumor tissues than para-carcinoma tissues." (PMID 31969492, 2020). "Actually, the data collected from TCGA database also proved the upregulation of UBE2T in tumor tissues (50 normal tissues vs. 374 tumor tissues, or 50 normal tissues vs. 50 matched tumor tissues, P < 0.001)." (PMID 31969492, 2020). "We identified increased levels of TTLL12, CDC16 and UBE2T in tumor samples from 103 patients with diffuse GC (M1) (p <0.001 for all analyzes)." (PMID 33351778, 2020). "Increasing evidence illustrated that, as one of the important members in the ubiquitin-protease system, UBE2T is closely related to cell proliferation, apoptosis, immune response, and tumor occurrence." (PMID 31969492, 2020). "The radioresistant role of UBE2T was examined by colony formation assays in vitro and xenograft tumor models in vivo." (PMID 33087136, 2020). "The fact that the prevention of SUMOylation of UBE2T (K8R mutation) has similar effect on properties of HepG2 cells with SENP1 suggests the deSUMOylation as the mechanism of SENP1 to induce UBE2T then the tumor progression." (PMID 31969492, 2020).
tumor (continued). "In conclusion, our study demonstrated that SENP1 and UBE2T were positively related and functioned as tumor promoters." (PMID 31969492, 2020). "Ubiquitin-conjugating enzyme E2T (UBE2T) is a member of the E2 family in the ubiquitin-proteasome pathway and a vital regulator of tumour progression, but its role in GBM is unclear." (PMID 32491994, 2020). "Taken together, all the findings above demonstrated that restoration of miR-1305 inhibited HCC tumor growth in vitro and in vivo, primarily due to the suppression of UBE2T." (PMID 31128423, 2019). "On the 14th day, the tumor volume and weight of mice were noted to significantly decrease by the silencing of UBE2T." (PMID 31128423, 2019). "Following miR-1305 mimic treatment with UBE2T, the nuclei staining of tumor cells became lighter, mitosis was attenuated, tumor tissue was necrotic, and fibrous tissue around the necrotic area was proliferated to different degrees." (PMID 31128423, 2019). "Most studies have focused on mutations in or overexpression of numerous E3 ubiquitin ligases that result in tumor suppression, while few have examined the effects of ubiquitin-conjugating enzymes (E2 enzymes) such as UBE2T." (PMID 28427240, 2017). "Next, we performed in vivo studies to confirm the effects of UBE2T on tumor formation and growth observed in the in vitro experiments." (PMID 28427240, 2017). "Here, suppression of UBE2T inhibited the ubiquitin-proteasome pathway and c-Myc expression, thereby inhibiting tumor growth." (PMID 28427240, 2017). "UBE2T was variably expressed in the cytoplasm of tumor cells in 140 out of the 149 samples, with higher expression in the peripheral region than in the central region of the typical cancer nest." (PMID 26943030, 2016). "Chi-square analysis showed that the UBE2T positive-expression ratio in tumor tissue was higher than that in adjacent normal tissue (P<0.001)." (PMID 26943030, 2016). "The potential oncogenic function of elevated UBE2T is likely to be polyubiquitination and subsequent proteasomal degradation of the E3 RING ligase BRCA1 — a primary tumour suppressor associated with mammary carcinogenesis." (PMID 27729585, 2016). "Recent studies have shown that UBE2T is highly expressed in tumor tissues and promotes carcinogenesis, implicating that UBE2T plays a role in the malignant tumor phenotype." (PMID 26943030, 2016). "Meanwhile, we found that patients whose tumor tissue showed high UBE2T expression had shorter overall survival time than those with low UBE2T expression, using Kaplan–Meier analysis and log-rank test (P=0.006)." (PMID 26943030, 2016). "Collectively, both in vivo and in vitro data strongly showed the biological role of UBE2T as a promoter of tumor growth and an inducer of EMT and metastasis in PCa." (PMID 26308072, 2015). "In contrast, silencing UBE2T expression inhibited tumor growth and induced a decrease in tumor weight and volume." (PMID 26308072, 2015). "In summary, we have for the first time achieved that UBE2T overexpression was sufficient to induce EMT of PCa cells as well as promote tumor growth and metastasis in vivo." (PMID 26308072, 2015). "We further demonstrated that UBE2T promotes proliferation, invasion, tumor formation and metastasis of PCa cells." (PMID 26308072, 2015). "Consistent with the notion that EMT is essential for tumor cells separating from the solid tumors and invading into distant sites, all of these characteristics induced by UBE2T in vitro culminated to increased numbers of distant metastases in vivo." (PMID 26308072, 2015). "Overexpression of UBE2T in PCa cells robustly promotes cell proliferation, migration and invasion in vitro and tumor growth and metastasis in vivo." (PMID 26308072, 2015). "Xenograft mouse model studies showed that overexpression of UBE2T promotes whereas UBE2T depletion inhibits tumor formation and metastasis significantly." (PMID 26308072, 2015).
tumor (continued). "By H&E staining for tumors formed in xenograft mouse model, we found that tumor cells overexpressing UBE2T showed mesenchymal-like morphology." (PMID 26308072, 2015). "Overexpression of UBE2T significantly accelerated tumor growth and induced an increase in tumor weight and volume." (PMID 26308072, 2015). "Prior studies have reported the opposite directionality that UBE2T can stimulate ERK signalling in several tumour models, suggesting that the ERK‐UBE2T relationship may be context‐dependent or potentially bidirectional." (PMID 41486508, 2026). "Finally, the ROC curve was constructed to verify the accuracy of UBE2T expression in predicting prognosis, as shown in Fig. B. The variable UBE2T had a sure accuracy in predicting the prognosis of tumor and normal patients (AUC=0.961, CI=0.928–0.994)." (PMID 39367897, 2025). "It is suggested that the expression of UBE2T may be related to tumorigenesis and can be used as a marker for tumor diagnosis." (PMID 39367897, 2025). "UBE2T, which is involved in ubiquitination and DNA damage repair, contributes to genomic stability, and its overexpression has been linked to poor prognosis in various cancers, including LIHC, suggesting a role in tumor progression and therapy resistance." (PMID 40251374, 2025). "The expression of UBE2T was higher in UCEC tumor tissues than in adjacent tissues (p= 0.0048)." (PMID 39367897, 2025). "The study results suggest that upregulation of UBE2T may suppress the body’s anti-tumor immune response, making UBE2T a potential target for tumor immunotherapy." (PMID 39367897, 2025). "Additionally, considering the enhanced efficacy of MFP in immunocompetent models and the impact of KRASG12D on tumor immunity, further investigation into the role of targeting UBE2T in modulating antitumor immune responses is required." (PMID 39970873, 2025). "UBE2T is an E2 enzyme with E2 and E3 ligase activity acting as an oncogene in various tumour types." (PMID 38243224, 2024). "Furthermore, high UBE2T levels reduce immune cell infiltration, such as T and B cells, impairing the immune system’s ability to recognize and eliminate tumor cells, thereby inhibiting the body’s antitumor immune response." (PMID 39791716, 2024). "Notably, the combination of TMZ with UBE2T inhibitors resulted in significantly greater tumor growth inhibition in experimental settings." (PMID 39791716, 2024). "Furthermore, UBE2T accelerates cancer progression by promoting the degradation of tumor suppressors through ubiquitination." (PMID 39791716, 2024). "This correlation may arise from variations in tumor cell types and extracellular conditions, highlighting the need for ongoing investigation into these mechanisms, which will be crucial for future UBE2T research." (PMID 39791716, 2024). "In addition to the previously discussed tumor types, UBE2T plays a significant role in various other cancers." (PMID 39791716, 2024). "1,2,3,4,6-O-Pentagalloylglucose 18’s tumor-suppressive activity is attributed to its multiple galloyl groups, which contain hydroxyl groups that specifically bind to the active site of UBE2T, notably at cysteine residue Cys86, with a dissociation constant (KD) of 23.94 nmol/L." (PMID 39791716, 2024). "One key alteration gene (UBE2T) was differently expressed between tumor specimens and normal specimens, suggesting that this gene may be a latent prognosis predictor for ES stufferers." (PMID 36910645, 2023). "In in vivo experiments, it was found that UBE2T knockdown inhibits the tumor growth in LUAD." (PMID 35543375, 2022). "Accumulating evidence has displayed that UBE2T is related to tumor progression." (PMID 35543375, 2022). "The DEGs can probably be used as potential predictors for stage-I LUAD worse prognosis and UBE2T may be a potential tumor promoter and target for treatment." (PMID 35444699, 2022).
tumor (continued). "We first analyzed UBE2T across 33 tumor types in The Cancer Genome Atlas (TCGA) project." (PMID 36357897, 2022). "UBE2T mediated Mule ubiquitination and degradation, thereby accelerating tumor invasion in HCC." (PMID 36357897, 2022). "Overexpression of UBE2T has been detected in different tumor types." (PMID 35444699, 2022). "However, the growth of transplanted tumours was significantly inhibited after knockout of the UBE2T gene." (PMID 36088429, 2022). "Moreover, the loss-of-function assay results revealed that UBE2T knockdown suppressed LUAD cell proliferation, migration, and invasion in vitro and tumor growth in vivo." (PMID 35543375, 2022). "The UBE2T immunoreactivity was mainly seen in the cytoplasm of tumor cells." (PMID 34461934, 2021). "We further verified the effect of UBE2T on tumor growth in vivo." (PMID 33323973, 2021). "UBE2T was highly expressed in LUAD tumor tissues, in contrast, NEDD4L was lowly expressed." (PMID 34838005, 2021). "We found that increased tumor growth in vivo triggered by FLAG-UBE2T could be reversed by simultaneous transfection of HA-NEDD4L, due to overexpression of NEDD4L caused UBE2T reduction." (PMID 34838005, 2021). "UBE2T over-expression has been found in different tumour types." (PMID 32491994, 2020). "Interestingly, subsequent studies showed that UBE2T downregulation inhibited the proliferation, migration, and invasion of many types of tumor cells and that its depletion significantly suppressed tumor formation and the metastasis of malignancies." (PMID 32025379, 2020). "Thus, we investigated UBE2T expression levels in pre-RT biopsy tumor specimens and analyzed the relationship between UBE2T levels and the radiosensitivity of metastatic sites." (PMID 33087136, 2020). "Notably, UBE2T functions as a tumour promoter in GBM in vivo, making it a potential therapeutic target." (PMID 32491994, 2020). "Furthermore, upregulation of UBE2T in the presence of miR-1305 mimic repressed tumor volumes and weights compared to miR-1305 scramble treatment with UBE2T upregulation." (PMID 31128423, 2019). "Recent studies have shown that disruption of UBE2T expression could directly lead to Fanconi anemia as well as an increase in tumor cell sensitivity to crossing-link agents, by interfering with the DNA damage-repair response." (PMID 26943030, 2016). "Additionally, exploring multi-targeted combination strategies involving UBE2T inhibitors with existing therapies could lead to more comprehensive tumor suppression." (PMID 39791716, 2024). "NOTCH2NL, MYBL2, and UBE2T were reported to be involved in tumorigenesis, while CXCR4 and IL18R1 were associated with immune response and pathway activation, indicating SRSF1 may take part in MM progression via tumor-related pathways." (PMID 37206090, 2023). "Therefore, we believe that UBE2T promotes the growth of transplanted tumours in vivo." (PMID 36088429, 2022). "Our findings were consistent with previous results that UBE2T may serve as a tumor promotor." (PMID 36245987, 2022). "Previous studies have hypothesized that UBE2T may contribute to a variety of tumor forms." (PMID 36245987, 2022). "Finally, IHC staining of tumor tissues revealed that UBE2T-expressing tumor had increased proliferation index (increased Ki-67 and decreased P21), reduced apoptosis index (C-Cas3) and increased p-AKT expression, which was abrogated by simultaneous transfection of HA-NEDD4L." (PMID 34838005, 2021). "Moreover, UBE2T depletion suppressed the growth of GBM subcutaneous tumours in vivo." (PMID 32491994, 2020). "Therefore, we aimed to further explore whether restoration of miR-1305 inhibited HCC tumor growth and attenuated the Akt-signaling pathway and whether decreased Akt signaling was mediated by UBE2T." (PMID 31128423, 2019). "They develop a nano co-delivery system combining F-127, the UBE2T inhibitor PGG, and the KRASG12D inhibitor MRTX1133, inducing significant tumor regression and durable therapeutic responses in KRASG12D-mutant PDAC." (PMID 39970873, 2025).